TLR4 (toll like receptor 4)
Diseases named in the same sentence as TLR4 in open-access papers (continued):
Sharing a sentence is not in itself a finding about the gene and the disease.
gram-negative bacterial infections (continued). "In contrast, overexpressing TLR4 seemed to resist gram-negative bacterial infections." (PMID 37443803, 2023). "Thus, TLR2 and TLR4 have been demonstrated to protect against Gram-positive or Gram-negative bacterial infection by sensing the respective structural components peculiar to each bacterium." (PMID 33763386, 2021). "Our prediction is that the stimulation of TLR4-bearing vagal (and/or spinal) neurons supplying the airways during a Gram-negative bacterial infection would trigger an efferent response, probably involving the release of CGRP, aimed at containing inflammation and favoring bacterial clearance." (PMID 33318075, 2021). "The ability of gram-negative bacterial infections to promote NSCLC progression by a Toll-like receptor 4 (TLR4)/myeloid differentiation primary response 88 (MyD88) and IL-33 pathway may be related to increased glycolysis by the induction of GLUT1." (PMID 31130612, 2019). "For example, TLR4-deficient or spontaneous TLR4 mutants (C3H/HeJ and C57/10ScCr) were not able to respond to LPS and suppressed Gram-negative bacterial infection." (PMID 30769918, 2019). "TLR4 plays a central role in defense against Gram-negative bacteria; however, mutations on the TLR4 gene or TLR4-deficient mice have been linked to hypo-responsiveness to LPS and high susceptibility to Gram-negative bacterial infections." (PMID 29491865, 2018). "Of note, TLR4 and IL-33 expressions were positively associated with Ki-67 proliferative index (PI) and expressions of CSC-related gene CD133 in NSCLC patients with gram-negative bacterial infection." (PMID 29568370, 2018). "Increased TLR4 expression may account for the resistance of mice to Gram-negative bacterial infection, for it elicits stronger immune response from the host." (PMID 26286454, 2015). "However, although Gram-negative bacterial infection is primarily regulated by TLR-4, TLR-2 activation is thought to play an import modulating role." (PMID 25025775, 2014). "Thus, TLR4 expression levels can vary with different clinical conditions such as Gram-negative bacterial infections." (PMID 23170858, 2012). "During systemic gram-negative bacterial infections, lipopolysaccharide (LPS) ligation to the hepatic Toll-like receptor-4 complex induces the production of hepatic acute phase proteins that are involved in the host response to infection and limit the associated inflammatory process." (PMID 17134499, 2006). "The Toll-like receptor 4 (TLR4) signaling pathway plays a central role in the prompt defense against infectious challenge and provides immediate response to Gram-negative bacterial infection." (PMID 36678520, 2022). "A recent report documented that TLR4-TRIF signaling and the IRF-3-mediated type I IFN response play important roles for in vivo IL-1β processing and production in response to Gram-negative bacterial infection." (PMID 32373120, 2020). "The development of innate immune responses against Gram-positive and Gram-negative bacterial infections is launched by the activation of TLR2 and TLR4, respectively." (PMID 32466097, 2020). "We observed higher TLR4, IL-33 and CD133 expressions in NSCLC patients with gram-negative bacterial infection." (PMID 29568370, 2018). "Lipopolysaccharide (LPS), an endotoxin enriched in the cell wall of gram-negative bacteria, binds Toll-like receptor 4 (Tlr-4) and is widely used to model gram-negative bacterial infections." (PMID 34394055, 2021). "For example, in the presence of Gram-negative bacterial infection, LPS could obviously upregulate the expression of PCSK9, while PCSK9 could further enhance the inflammatory reactions through modulating the TLR-4/NF-κB signaling pathway." (PMID 33123601, 2020). "TLR4 can recognize LPS of gram-negative bacteria, which is one of the main ways for the host to recognize gram-negative bacterial infection." (PMID 31671112, 2019).
gram-negative bacterial infections (continued). "Lbp is involved in the acute phase immunologic response to Gram-negative bacterial infections through binding to bacterial lipopolysaccharide (LPS), thereby eliciting immune responses by presenting the LPS to the cell surface pattern recognition receptors CD14 and Tlr4." (PMID 24063402, 2013).
cervical carcinoma (57 papers, 2011 to 2025). A carcinoma arising from either the exocervical squamous epithelium or the endocervical glandular epithelium. "In a study of Tunisian women with cervical cancer compared with controls, the TLR-4 polymorphism Asp299Gly (rs4986790) was found to be associated with a higher risk of cervical cancer as well." (PMID 41374999, 2025). "Alterations in the pattern of TLR4 expression are associated with the occurrence, development and progression of cervical cancer and are related to HPV infections." (PMID 39208235, 2024). "Our study highlights a new potential pathogenetic aspect of HPV-related cervical cancer development, taking into consideration the role of TLR4 as a new diagnostic, prognostic, and potentially therapeutic biomarker, in addition to the presence of HPV." (PMID 39451550, 2024). "TLR4 was expressed at high levels in cervical cancer cells and was associated with the clinical FIGO stage and lymph node metastasis." (PMID 38463226, 2024). "In a study involving 122 Tunisian women with cervical cancer compared with 260 healthy control, the TLR4 polymorphism Asp299Gly (rs4986790) was found to be associated with a higher risk of cervical cancer." (PMID 37370894, 2023). "It was reported that heterozygous genotype (CT) and mutant allele (T) of TLR4 rs1927911 increased the risk of cervical cancer and HPV16/18 infection, while the role of SNP rs10116253 and rs10759931 in the HPV infection was not clear." (PMID 36915050, 2023). "The chronic inflammation mediated by TLR4/iNOS and TLR4/MYD88/NF-κB signaling pathway was associated with HPV-related cervical cancer." (PMID 36915050, 2023). "Several studies have revealed that TLR4 expression is upregulated in cervical cancer cells compared with other TLRs and causes apoptosis resistance." (PMID 35918631, 2022). "The TLR4 haplotype GTAC was linked with a significant increase in cervical cancer risk in addition to the TLR9 haplotype GATC that also showed association with increased HPV 16 and 18 infections." (PMID 31278284, 2019). "Intriguingly, another TLR4 haplotype GCAG showed a significant association with decreased cervical cancer risk as well as acquiring the hrHPV infection, suggesting its protective role." (PMID 31278284, 2019). "The potential mechanisms underlying POL-P3b-induced protection of intestinal DC from cervical cancer-induced apoptosis were detected with Western blotting evaluation of expression levels of TLR4 and relevant proteins for apoptotic signaling pathway." (PMID 31277622, 2019). "In cervical carcinoma, some authors have demonstrated high TLR4 expression, whilst others demonstrated low TLR4 expression, linked to histological grade." (PMID 29416610, 2018). "Our results also showed that the occurrence and development of cervical cancer were associated with the expression of TLR4 in HPV16-infected cervical lesions, but the severity of cervical lesions did not necessarily correlate with gene expression." (PMID 29263932, 2017). "Polymorphisms of TLR genes have been associated with many diseases and may be a cause of TLR4 disfunction and a risk factor linked to cervical cancer." (PMID 39451550, 2024). "However, there are very few studies on the impact of TLR4 gene polymorphisms on the pathomorphological features or course of cervical cancer." (PMID 37370894, 2023). "Furthermore, we observed the 3′ UTR heterozygous genotype GC of TLR4 rs11536889 to be associated with increased risk of cervical cancer in our study subjects." (PMID 31278284, 2019). "Together, these results indicate that TLR4/NO signaling pathway activation in cervical cancer is associated with HR-HPV infection and may be involved in the regulation of the local cervical immune microenvironment and the pathogenesis of cervical cancer." (PMID 28626766, 2017).
cervical carcinoma (continued). "They found that the key genes of TLR4/NO pathway, such as TLR4, NF-κBp65, and iNOS, are highly expressed in HR-HPV-positive cervical cancer tissues and cells, strongly suggesting that the TLR4/NO signal pathway may be associated with the HR-HPV infection." (PMID 29263932, 2017). "To further investigate whether IGHG1 deficiency inhibited the TLR4 signaling pathways in cervical cancer cells, we examined nuclear translocation of NF-κB subunit p65 in Hela cells with immunostaining after LPS treatment." (PMID 25179302, 2014). "We investigated whether TLR4 could associate with IgG in cervical cancer cells." (PMID 25179302, 2014). "The signal transduction pathways of TLR-4 and TLR-9 single-nucleotide polymorphisms (SNPs) have been related to HPV infection and cervical cancer." (PMID 41374999, 2025). "Overexpression of TLR4 was also found in precancerous and malignant cervical cancer specimens, as well as in the human cervical cancer line (HeLa)." (PMID 38812510, 2024). "Among the diversity of receptors, TLR10 is the most recently described, generating controversy regarding its function; TLR4 recognizes exogenous pathogens and is closely linked to the growth of HPV-positive cervical cancer." (PMID 39208235, 2024). "Previous studies showed that TLR4 expression was higher in invasive cervical cancers than in CIN lesions and that it was lower in normal cervical tissues." (PMID 39451550, 2024). "In a study conducted in the United States, TLR2 and TLR4 expression levels were found to be greater in cervical cancer and premalignant lesions than in normal controls." (PMID 39208235, 2024). "In studies on the occurrence of cervical cancer, it has been found that TLR4 and 9 levels are crucial for initiating innate immune responses owing to the toxic effects of target cells and the induction of cytokine synthesis." (PMID 38812510, 2024). "The expression of TLR2 and TLR4 immune receptors is higher in human cervical cancer than that of other TLRs." (PMID 39621646, 2024). "A limitation of such a study is that the expression level of TLR4 in different tissues by IHC cannot support the view that TLR4 plays a role in the occurrence and development of cervical cancer." (PMID 39451550, 2024). "Previous studies showed that TLR4 expression was higher in invasive cervical cancers than in CIN lesions and lower in normal cervical tissues." (PMID 39451550, 2024). "Nevertheless, recent reports show that TLRs, particularly TLR4, are involved in the tumor initiation and progression of cancers, such as cervical cancer." (PMID 37174723, 2023). "On the other hand, TLR4 has higher expression levels in cervical cancer cells compared to normal cells and its expression levels correlates with increased risk of lymph node metastasis." (PMID 35468924, 2022). "The variant genotypes of TLR4 rs1156889 and TLR9 rs187084 and rs1927911 SNPs were found to be associated with the increased risk of developing cervical cancer among Indian women." (PMID 35330409, 2022). "It was found previously that TLR9 rs187084, as well as TLR4 rs4986790 and rs1927911 SNPs, showed an association with HPV16/18 infection in cervical cancer cases." (PMID 36231099, 2022). "Here, we sought to further dissect the function of the TLR pathway in a cervical cancer cell line focusing on the roles of TLR4 and SARM1 on cell survival and cisplatin resistance." (PMID 35468924, 2022). "In another study in India showed the TLR4 and TLR9 polymorphisms and haplotypes with hrHPV infection and cervical cancer risk." (PMID 34837895, 2021). "Overall, we showed that icariin efficiently inhibits the inflammation, proliferation, invasion, as well as promotes apoptosis and immunity in cervical cancer by inhibiting TLR4/MyD88/NF-κB and Wnt/β-catenin pathways." (PMID 33849528, 2021).
cervical carcinoma (continued). "The TLR4 immune receptor is expressed in human cervical cancer HeLa cells with a frequency 100 times higher than other TLRs, proving a correlation between TLR4 and cervical cancer progression." (PMID 34117331, 2021). "Different cell lines and tissue samples from patients with head and neck, esophageal, stomach, colon and rectum, liver, pancreatic, skin, breast, ovarian, and cervical cancer showed an increase in TLR4 expression." (PMID 34631699, 2021). "In contrast, LPS can bind to its receptor TLR4 and promote the proliferation of cervical cancer cells through the MyD88 and NF-κB pathways." (PMID 33456361, 2021). "Toll-like receptor 4 (TLR4) expression supports the claim of a distinct relation between tumor formation and HPV-positive cervical cancer, suggesting that TLR4 somehow enables the formation of a local immunosuppressive microenvironment." (PMID 33747035, 2021). "Our finding is consistent with predecessor's studies and confirmed that ICA suppressed the tumor progression of cervical cancer by inhibiting TLR4/MyD88/NF-κB and Wnt/β-catenin pathways in vitro and in vivo." (PMID 33849528, 2021). "Their results showed that mutant alleles of TLR2 rs3775290, TLR4 rs7873784, and TLR9 rs352140 were associated with increased cervical cancer risk." (PMID 34837895, 2021). "Recent studies suggested that the overexpression of the TLR4 was correlated with immune escape and apoptosis resistance in cervical cancer." (PMID 33849528, 2021). "In a study concerning cervical cancer, it was registered that TLR4 haplotype GTAC and TLR9 haplotype GATC are associated with an increased risk of cervical cancer, while TLR4 haplotype GCAG is associated with a decreased risk." (PMID 34439871, 2021). "For the part of mechanism exploration, we showed that ICA inhibits the inflammation, proliferation, migration, and invasion, as well as promotes apoptosis and immunity in cervical cancer through impairment of TLR4/MyD88/NF-κB and Wnt/β-catenin pathways." (PMID 33849528, 2021). "In the present study, ICA has remarkably reduced the expression levels of TLR4, MyD88, NF-κB p65, Wnt 1, and β-catenin in cervical cancer SiHa cells." (PMID 33849528, 2021). "The correlations between ICA and expression levels of TLR4/MyD88/NF-κB and Wnt /β-catenin signaling pathway were observed, for purpose of providing novel insight into cervical cancer." (PMID 33849528, 2021). "TLR4 has been reported to facilitate the development of many inflammation-induced cancers such as cervical cancer." (PMID 34226529, 2021). "The aim of this study was to further explore the role of TLR4 in HPV-related cervical cancer in vivo by using a nude mouse xenograft model." (PMID 32095158, 2020). "In this study, a nude mouse xenograft model was used to further investigate the role of TLR4 in HPV-related cervical cancer in vivo to verify TLR4 function in a multidimensional manner." (PMID 32095158, 2020). "In this study, our data suggested that TLR4 expression is closely correlated with HPV-positive cervical cancer." (PMID 32095158, 2020). "This study further provides evidence for the clinical treatment of cervical cancer by targeting TLR4-relevant molecules." (PMID 32095158, 2020). "TLR4 expression is closely associated with the tumorigenesis and growth of HPV-positive cervical cancer; TLR4 promotes HPV-positive cervical tumor growth and facilitates the formation of a local immunosuppressive microenvironment." (PMID 32095158, 2020). "In the present study, we investigated the role of the common TLR4 and TLR9 SNPs in susceptibility to HPV infection and cervical cancer among the study subjects from Gujarat, India." (PMID 31278284, 2019). "CC and CT genotypes of TLR4 rs11536889 and rs1927911 respectively, and TC, CC genotypes of TLR9 rs187084, as well as minor alleles of TLR4 rs4986790 and TLR9 rs187084, were associated with the increased risk of cervical cancer." (PMID 31278284, 2019).
cervical carcinoma (continued). "In conclusion, the present study revealed association of TLR4 and TLR9 polymorphisms and haplotypes with hrHPV infection and cervical cancer risk." (PMID 31278284, 2019). "Among cervical cancer cases, TLR4 and TLR9 haplotypes revealed an accumulated frequency of 85% and 83.1% respectively." (PMID 31278284, 2019). "TLR4 haplotype GTAC and TLR9 haplotype GATC were associated with the increased risk of cervical cancer while TLR4 haplotype GCAG was associated with the decreased risk." (PMID 31278284, 2019). "Reports on the influence of TLR4 and TLR9 single nucleotide polymorphisms (SNPs) in cervical cancer susceptibility are limited as well as conflicting." (PMID 31278284, 2019). "Although our results suggest a significant role of TLR4 and TLR9 polymorphisms in cervical cancer, the study has some vital limitations too." (PMID 31278284, 2019). "Our results suggest moderate to strong impact of TLR4 and TLR9 polymorphisms in susceptibility to hrHPV infection and cervical cancer." (PMID 31278284, 2019). "The present study was therefore designed to ascertain the role of TLR4 and TLR9 SNPs and haplotypes to hrHPV infection and cervical cancer susceptibility." (PMID 31278284, 2019). "First, we observed that the adaptor molecule MyD88 was downregulated whereas SARM1 and TLR4 were upregulated in all three cervical cancer cell lines relative to normal keratinocytes." (PMID 29472602, 2018). "Conversely, a positive correlation has been detected between the expression of TLR4, TLR7, and TLR9 and the development and progression of CIN and cervical carcinoma associated with HPV169." (PMID 29472602, 2018). "The correlation analysis showed that the expression of TLR4 in cervical cancer is irrelevant to HPV16 E7 (r=0.121, P=0.0612)." (PMID 29263932, 2017). "Of the four kinds of TLRs, the most significant difference was found in TLR4 expression, which was upregulated by 3.1–4.5 times in the cervical cancer group compared with the control group." (PMID 28626766, 2017). "Our previous studies showed that the expression of TLR4 in cervical cancer is related to the occurrence, development, and growth of cervical cancer cells." (PMID 29263932, 2017). "In our study, upregulation of TLR4 in cervical cancer was the most significant among the TLRs examined (including TLR3, TLR4, TLR7, and TLR8)." (PMID 28626766, 2017). "In conclusion, the expression levels of key genes in the TLR4/NO signaling pathway are upregulated in HR-HPV-positive cervical cancer tissue." (PMID 28626766, 2017). "We further verified the activation of the TLR4/NO signaling pathway in cervical cancer cell lines, including CaSki (HPV16+), HeLa (HPV18+), and C33a (HPV−) cells." (PMID 28626766, 2017). "But a few studies also showed that TLR4 expression was downregulated in cervical cancer, suggesting that HPV can inhibit TLR4 expression." (PMID 28626766, 2017). "Alternatively, a recent study demonstrated that cancer-derived IgG promotes cervical cancer cell proliferation by enhancing pro-inflammatory cytokine production in response to lipopolysaccharide (LPS) binding to Toll-like receptor 4 (TLR4)." (PMID 28536629, 2016). "To confirm that TLR4 expression played a key role in IgG positively regulated LPS-induced proinflammatory cytokine production, we analyzed TLR4 expression in human cervical cancer tissues and normal cervical tissues with immunohistochemistry." (PMID 25179302, 2014). "Briefly, these findings demonstrate that cancer-derived IgG is a positive regulator of LPS-induced proinflammatory cytokine production via binding to TLR4 in cervical cancer cells." (PMID 25179302, 2014). "We further evaluated the role of TLR4 in IgG enhanced LPS-induced proinflammatory cytokine production of cervical cancer cells." (PMID 25179302, 2014). "In this study, we demonstrated that IgG expression was significantly altered after exposure to LPS in cervical cancer cells, suggesting that IgG was potentially involved in regulation of TLR4 signaling." (PMID 25179302, 2014).